MYRF (myelin regulatory factor)
Description:
[Myelin regulatory factor]: Constitutes a precursor of the transcription factor. Mediates the autocatalytic cleavage that releases the Myelin regulatory factor, N-terminal component that specifically activates transcription of central nervous system (CNS) myelin genes. [Myelin regulatory factor, C-terminal]: Membrane-bound part that has no transcription factor activity and remains attached to the endoplasmic reticulum membrane following cleavage. [Myelin regulatory factor, N-terminal]: Transcription factor that specifically activates expression of myelin genes such as MBP, MOG, MAG, DUSP15 and PLP1 during oligodendrocyte (OL) maturation, thereby playing a central role in oligodendrocyte maturation and CNS myelination. Specifically recognizes and binds DNA sequence 5'-CTGGYAC-3' in the regulatory regions of myelin-specific genes and directly activates their expression. Not only required during oligodendrocyte differentiation but is also required on an ongoing basis for the maintenance of expression of myelin genes and for the maintenance of a mature, viable oligodendrocyte phenotype.
Synonyms: C11orf9; MRF; Ndt80; pqn-47; 11orf9; CUGS; MMERV; NNO1
Tractability: Antibody: UniProt predicts a signal peptide or a membrane-spanning region.
Gene: Protein-coding gene on chromosome 11 (61,752,593 to 61,788,518, forward strand). Ensembl gene ENSG00000124920.
Subcellular location: Endoplasmic reticulum membrane (Myelin regulatory factor); Nucleus (Myelin regulatory factor, N-terminal); Cytoplasm; Endoplasmic reticulum membrane (Myelin regulatory factor, C-terminal)
Subcellular location (Human Protein Atlas): Nucleoplasm; Cytosol
Gene Ontology:
Molecular function: DNA-binding transcription factor activity; sequence-specific DNA binding; DNA binding
Biological process: central nervous system myelin maintenance; central nervous system myelination; oligodendrocyte development; oligodendrocyte differentiation; positive regulation of DNA-templated transcription; positive regulation of myelination; protein autoprocessing; positive regulation of oligodendrocyte differentiation; regulation of DNA-templated transcription; response to cocaine; response to immobilization stress
Cellular component: cytoplasm; endoplasmic reticulum membrane; nucleus
Genetic constraint (gnomAD): Loss-of-function variants: 16 observed, 112.85 expected, observed/expected ratio (o/e) 0.14, 90% interval 0.095 to 0.22. The upper end of that interval is the gene's LOEUF score, 0.22, which puts it in group 1 of 6, group 1 being the genes least tolerant of losing a copy. Missense variants: 1,093 observed, 1,466.2 expected, observed/expected ratio (o/e) 0.75, 90% interval 0.71 to 0.78. Synonymous variants: 605 observed, 609.97 expected, observed/expected ratio (o/e) 0.99, 90% interval 0.93 to 1.06.
Gene-disease validity (ClinGen):
ClinGen rates the evidence that MYRF causes each of these diseases.
cardiac-urogenital syndrome (autosomal dominant): Definitive. Cardiac-urogenital syndrome is characterized by partial anomalous pulmonary venous return in association with tracheal anomalies, pulmonary hypoplasia, congenital diaphragmatic hernia, thyroid fibrosis, thymic involution, cleft spleen, penoscrotal hypospadias, and cryptorchidism (Pinz et al., 2018).
Homologues: Orthologues: macaque MYRF (98% identical), dog MYRF (90% identical), rat Myrf (89% identical), mouse Myrf (89% identical), rabbit MYRF (81% identical), chimpanzee MYRF (81% identical), guinea pig MYRF (77% identical), tropical clawed frog myrf (57% identical), zebrafish myrf (33% identical), Drosophila melanogaster CG3328 (32% identical), Caenorhabditis elegans myrf-1 (22% identical), Caenorhabditis elegans myrf-2 (22% identical). Paralogues in human: MYRFL (34% identical).
Diseases named in the same sentence as MYRF in open-access papers:
MYRF is named in the same sentence as 67 diseases in open-access papers, as found by Europe PMC text mining. Sharing a sentence is not in itself a finding about the gene and the disease. The quoted sentences say what the papers report.
nanophthalmos (17 papers, 2019 to 2026). "Overall, hypomorphic MYRF alleles underlie isolated nanophthalmos, supporting a tissue-specific threshold effect and highlighting unique roles for the MYRF C-terminus in the RPE." (PMID 41746734, 2026). "Heterozygous variants in MYRF are associated with cardiac-urogenital syndrome, nanophthalmos and mild encephalopathy with reversible myelin vacuolization." (PMID 41393291, 2025). "Since MYRF is also expressed in the retinal pigment epithelium, some variants in the MYRF gene are associated with ocular disorders such as nanophthalmos." (PMID 36695166, 2023). "Shortly after, Xiao and colleagues, investigating another large family with inherited nanophthalmos, revealed an additional truncating mutation in MYRF (c.3377delG, p.G1126Vfs*31)." (PMID 36013096, 2022). "According to the authors, the MYRF loss-of-function variant described in this patient was the first case combining gonadal dysgenesis and nanophthalmos phenotypes." (PMID 36013096, 2022). "To date, six genes (PRSS56, MFRP, TMEM98, CRB1, BEST1, and MYRF) have been implicated in familial forms of nanophthalmos, with PRSS56 and MFRP mutations being the most prevalent among multiple cohorts." (PMID 33755662, 2021). "Two recent human genetics studies identified that haplotypes of MYRF C-terminal variants can cause nanophthalmos, a potentially devastating eye condition." (PMID 33950834, 2021). "We went on to identify protein partners of TMEM98 and found that it interacts with a protein called MYRF, mutations in which also cause nanophthalmos." (PMID 32236127, 2020). "Here we report a patient with nanophthalmos and a novel mutation in the recently discovered MYRF gene." (PMID 33004036, 2020). "MYRF itself has since been linked to nanophthalmos in humans and retinal degeneration in mice, similar to TMEM98." (PMID 31961879, 2020). "To evaluate the prevalence of MYRF mutations in high hyperopia and nanophthalmos, we systematically screened 60 independent cases of high hyperopia and nanophthalmos." (PMID 31048900, 2019). "Our analysis of unrelated high hyperopia and nanophthalmos probands suggests that variants in MYRF are an uncommon monogenic cause of these conditions." (PMID 31048900, 2019). "Taken together, we have provided strong evidence for a causal link between MYRF and high hyperopia/nanophthalmos." (PMID 31048900, 2019). "Here, we show that an inherited deleterious splice site mutation in MYRF that segregates with nanophthalmos in this family." (PMID 31048900, 2019). "We present multiple lines of evidence to implicate a deleterious variant in MYRF as the underlying cause of nanophthalmos in the family that we used to map the NNO1 locus." (PMID 31048900, 2019). "Our large family with nanophthalmos represents an expansion in phenotype of that seen in the newly described MYRF-associated syndrome." (PMID 31048900, 2019). "De novo variants in the myelin regulatory factor (MYRF), a transcription factor involved in the differentiation of oligodendrocytes, have been linked recently to the cardiac and urogenital syndrome, while familiar variants are associated with nanophthalmos." (PMID 36013096, 2022). "Heterozygous variants in MYRF are also associated with nanophthalmos." (PMID 36013096, 2022). "Familial cases of nanophthalmos due to disrupting variants of MYRF have also been identified." (PMID 36013096, 2022). "Additionally, several genes have been associated with nanophthalmos as part of a multisystem syndrome, including MYRF and FAM111A." (PMID 34573386, 2021). "We report clinical features in a patient with nanophthalmos and a Thr518Met MYRF mutation." (PMID 33004036, 2020). "The MYRF gene is itself associated with mutations leading to nanophthalmos." (PMID 32236127, 2020). "Nanophthalmos may present at an early age with features of angle closure glaucoma and a Thr518Met mutation in MYRF was detected in a patient with nanophthalmos." (PMID 33004036, 2020).
nanophthalmos (continued). "Interestingly, heterozygous mutations of MYRF in humans lead to nanophthalmos, suggesting loss of this protein has the opposite effect to the activation we suggest occurs in the Tmem98 deletion eyes." (PMID 32236127, 2020). "Together these data suggest that the Thr518Met variant in MYRF may cause nanophthalmos by destabilizing the fold of its DNA-binding domain and altering its function as a transcription factor." (PMID 33004036, 2020). "To determine whether other rare variants in MYRF were associated with nanophthalmos or high hyperopia, we identified individuals in The Genomic Ascertainment Cohort (TGAC), whose exome data were available from the ClinSeq project." (PMID 31048900, 2019). "C-terminal variants in the Myelin regulatory factor (MYRF) gene, a retinal pigment epithelium-derived (RPE-derived) transcription factor, lead to isolated nanophthalmos characterized by a small, though structurally sound eye." (PMID 41746734, 2026). "The MYRF LOF variant reported here in a child with gonadal dysgenesis and nanophthalmos is, to our knowledge, the first case with this combination of phenotypes." (PMID 35432193, 2022). "We have defined the diagnostic yield of sequencing the coding variants in PRSS56, MFRP, TMEM98, MYRF, CRB1, and BEST1 in a large cohort of patients with nanophthalmos and high hyperopia." (PMID 33203948, 2020). "While six genes have been implicated in this hereditary condition (MFRP, PRSS56, MYRF, TMEM98, CRB1,VMD2/BEST1), the relative contribution of these to nanophthalmos or to less severe high hyperopia (≥ + 5.50 spherical equivalent) has not been fully elucidated." (PMID 33203948, 2020). "Fifth, MYRF interacts with TMEM98, a gene recently implicated in nanophthalmos in 3 families, at both regulatory and direct protein-protein levels." (PMID 31048900, 2019). "To define the role of MYRF in the pathogenesis of nanophthalmos, we first systematically evaluated RNA expression in human ocular and adnexal tissues." (PMID 31048900, 2019). "We have used this novel pooled-exome and linkage-based approach to uncover the role of MYRF in the pathogenesis of nanophthalmos." (PMID 31048900, 2019). "We showed that MYRF interacts with and regulates expression of another membrane protein, TMEM98, which has been implicated in nanophthalmos." (PMID 31048900, 2019). "Our study establishes MYRF as a new disease gene for nanophthalmos and a regulator of eye development." (PMID 31048900, 2019). "We have further uncovered a role for MYRF in the early development of the RPE, and a regulatory and physical interaction with TMEM98 another RPE expressed gene implicated in nanophthalmos." (PMID 31048900, 2019). "Variants in MYRF, which underlies the NNO1 locus, have been identified an emerging syndrome featuring a congenital diaphragmatic hernia, cardiac and pulmonary vascular anomalies, urogenital anomalies, and nanophthalmos." (PMID 34573386, 2021). "Additionally, 2 MYRF splicing variants creating nonfunctional isoforms were found in families with isolated nanophthalmos." (PMID 41746734, 2026). "A reason for this might be the very recent description of the CUGS, as well as the separate detection of C-terminal MYRF variants in familiar cases of nanophthalmos without further CUGS symptoms and the different time points of diagnosis." (PMID 36013096, 2022). "Given that mouse MYRF functions as a transcription factor and is present in fetal RPE, we hypothesized that it might regulate transcription of other RPE-expressed genes associated with nanophthalmos in humans." (PMID 31048900, 2019). "While syndromic MYRF-OCUGS is associated with MYRF haploinsufficiency and not clearly associated with a particular protein domain, isolated nanophthalmos (structurally normal small eyes) may result from C-terminal variants that escape nonsense-mediated decay in ocular tissue." (PMID 41347118, 2026).
nanophthalmos (continued). "There is a wide phenotypic spectrum of MYRF-related disorders and there does not appear to be a clear genotype-phenotype association for MYRF-OCUGS, though variants affecting the C-terminus of the protein appear to be associated with isolated nanophthalmos." (PMID 41347118, 2026).
Encephalopathy (8 papers, 2018 to 2025). Encephalopathy is a term that means brain disease, damage, or malfunction. "MYRF Q403R mutation has been linked to encephalopathy with reversible myelin vacuolization, a much milder condition compared with birth defects." (PMID 33798553, 2021). "Recently, an inherited missense variant in MYRF (Q403R) has been reported as the cause of encephalopathy with reversible myelin vacuolization in a Japanese pedigree." (PMID 30532227, 2018). "Additionally, genetic risk factors are also suspected, such as RANBP2 in ANE and MYRF in mild encephalitis/encephalopathy with reversible splenial lesion (MERS)." (PMID 38528535, 2024). "Together with encephalitis/encephalopathy (MIM # 608329), these are the only syndromes in the MIM database associated with MYRF deficiency." (PMID 36695166, 2023).
congenital diaphragmatic hernia (6 papers, 2018 to 2023). A posterolateral defect of the diaphragm that allows passage of abdominal viscera into the thorax, leading to respiratory insufficiency and persistent pulmonary hypertension with high mortality. "MYRF emerged as a candidate gene from the study of different cohorts of patients with urogenital, cardiac, and pulmonary phenotypes, congenital diaphragmatic hernia, reversible refractory epilepsy, or ophthalmopathy." (PMID 37511771, 2023). "The initial descriptions of MYRF-related syndromic disease led to a new definition of a rare cardiac-urogenital syndrome [CUGS; Online Mendelian Inheritance in Man (OMIM) #618280] that includes CHD, genitourinary anomalies, congenital diaphragmatic hernia and pulmonary hypoplasia." (PMID 37584388, 2023).
hyperopia (6 papers, 2019 to 2025). A refractive error in which rays of light entering the eye parallel to the optic axis are brought to a focus behind the retina, as a result of the eyeball being too short from front to back. "Here, we present the case of a 46,XY patient with PGD, Scimitar syndrome, pulmonary vein malformation and severe hyperopia, who, to the best of our knowledge, is the first case involving eye, heart and genital defects due to a MYRF disruptive variant." (PMID 36013096, 2022). "Here, we report for the first time on a patient with a de novo stop-gain variant in MYRF (p.Q838*) associated with Scimitar syndrome, 46,XY partial gonadal dysgenesis (GD) and severe hyperopia." (PMID 36013096, 2022). "Whole-exome sequencing identified three novel truncation mutations in MYRF located in the linkage interval in three families with high hyperopia, including the family mapped to this locus." (PMID 31172260, 2019). "Nevertheless, MYRF-associated high hyperopia and NNO1 share common clinical features, such as high hyperopia, short axial length, and angle-closure glaucoma." (PMID 31172260, 2019). "These evidence all support that truncation mutations in the C-terminal region of MYRF are responsible for autosomal dominant high hyperopia in these families." (PMID 31172260, 2019). "Sixth, a syndromic patient with an MYRF loss-of-function variant also has small eyes and high hyperopia." (PMID 31048900, 2019). "Whole-exome sequencing in other 121 probands with high hyperopia identified additional novel mutations in MYRF within two other families: a de novo c.3274_3275delAG (p.Leu1093Profs*22) heterozygous mutation and a c.3194+2T>C heterozygous mutation." (PMID 31172260, 2019). "Our findings may provide useful clues to further elucidate the function of the critical myelin regulatory factor MYRF as well as the molecular pathogenesis of high hyperopia and its associated angle-closure glaucoma." (PMID 31172260, 2019). "WES and whole-genome sequencing identified novel truncation mutations in the C-terminal portion of MYRF, located inside the linkage interval of high hyperopia but outside the linkage interval of NNO1, in three unrelated families including the family whose mutation is mapped to this region." (PMID 31172260, 2019). "Our results may provide useful clues for further understanding the functional role of the C-terminal region of this critical myelin regulatory factor, as well as the molecular pathogenesis of high hyperopia and its associated angle-closure glaucoma." (PMID 31172260, 2019). "In addition, we identified an early truncating MYRF frameshift mutation, c.769dupC (p.S264QfsX74), in a patient with extreme axial hyperopia and syndromic features." (PMID 31048900, 2019). "It remains to be determined whether other rare or common variants in MYRF contribute to high hyperopia." (PMID 31048900, 2019). "The phenotypes associated with different MYRF variants may need further clarification, although our current study provides the strongest genetic evidence to date in support of the association between MYRF truncation mutation and high hyperopia." (PMID 31172260, 2019). "Therefore, MYRF-associated high hyperopia should be considered to have a separate locus." (PMID 31172260, 2019). "To our knowledge, we present the first case with a combination of three MYRF associated phenotypic features: heart defects (CHD, dextrocardia, anomalous pulmonary venous return), 46,XY PGD and severe hyperopia." (PMID 36013096, 2022). "Here, we report a novel, heterozygous de novo p.Q838* variant in MYRF in a patient with 46,XY partial gonadal dysgenesis (PGD), Scimitar syndrome and severe hyperopia, identified by whole genome analysis." (PMID 36013096, 2022). "All the three truncation variants identified in families with high hyperopia in the current study are located at the C-terminal of MYRF and absent in gnomAD database." (PMID 31172260, 2019).
hyperopia (continued). "Further study on these truncation mutations in the C-terminal portion of MYRF may not only reveal the molecular pathway contributing to high hyperopia but also provide a valuable avenue for investigating the role of MYRF C-terminal portion." (PMID 31172260, 2019).
Cardiac-urogenital syndrome (5 papers, 2022 to 2026). "In humans, MYRF haploinsufficiency causes a spectrum of congenital disorders collectively termed MYRF-related Cardiac Urogenital Syndrome, affecting the heart, lungs, and urogenital system, further highlighting its developmental importance." (PMID 41542402, 2026). "With the recent development of exome sequencing, pathogenic variants of MYRF had been considered as the cause of cardiac-urogenital syndrome (CUGS), 46,XY and 46,XX disorders/differences of sex development (DSDs), and nanophthalmos." (PMID 36467480, 2022). "In humans, MYRF is a key regulator of myelin development and is required for biosynthesis of oligodendrocytes; mutations in this gene are associated with a newly identified disorder, cardiac-urogenital syndrome, which is characterized by congenital heart defects including BAV." (PMID 35711915, 2022). "Haploinsufficiency in human MYRF leads to MYRF-Related Cardiac Urogenital Syndrome." (PMID 38963411, 2024). "For example, Cardiac Urogenital Syndrome (CUGS), a genetic condition caused by pathogenic variants in the MYRF gene, was initially characterized by congenital diaphragmatic hernia, congenital heart defects, and urogenital defects without clear ocular differences noted." (PMID 36980998, 2023).